FAAH (fatty acid amide hydrolase)
Diseases named in the same sentence as FAAH in open-access papers (continued):
Sharing a sentence is not in itself a finding about the gene and the disease.
social anxiety disorder (8 papers, 2021 to 2025). "In another clinical trial, performed on people with SAD (social anxiety disorder), an inhibitor of FAAH, JNJ-42165279 significantly improved the Liebowitz Social Anxiety Scale (LSAS) total score from baseline to end of study." (PMID 36835237, 2023). "A 12-week multi-center trial for social anxiety disorder was also performed with the JNJ-42165279 FAAH inhibitor." (PMID 37671673, 2023). "As such, while this trial suffered from technical issues, the outcome data do suggest some potential benefit of FAAH inhibition in the context of treating social anxiety disorder." (PMID 37671673, 2023). "Additionally, a clinical trial showed that FAAH inhibitors were effective anxiolytics for people with social anxiety disorder." (PMID 40332352, 2025).
Hypertension (7 papers, 2018 to 2024). The presence of chronic increased pressure in the systemic arterial system. "Our study aimed to examine the effects of hypertension and the chronic administration of the fatty acid amide hydrolase (FAAH) inhibitor URB597 on vascular function and the endocannabinoid system in spontaneously hypertensive rats (SHR)." (PMID 34063297, 2021). "As such, it would be interesting to examine the vascular effects of the chronic administration of a MAGL inhibitor or dual FAAH/MAGL inhibitor in hypertension." (PMID 34063297, 2021). "In both models of hypertension, we observed increases in FAAH activities in comparison to the respective normotensive control (+77% in SHR and +115% in DOCA), but no changes in MAGL activities." (PMID 32075117, 2020). "It inhibited the FAAH activity in both hypertension models, but had opposite effects on cardiac levels of various endocannabinoids and endocannabinoid-related lipids (decrease in SHR vs. increase in DOCA)." (PMID 32075117, 2020). "Thus, we cannot exclude a stronger antihypertensive effect of a dual FAAH/MAGL inhibitor in other models of hypertension." (PMID 37446125, 2023). "Prevention of the progression of hypertension induced by dual FAAH/MAGL inhibitors might be an additional beneficial property of such compounds when used for other indications." (PMID 37446125, 2023). "Consequently, it is necessary to consider other possible molecular targets for FAAH- and MethAEA-mediated signaling pathways in hypertension." (PMID 34063297, 2021). "Cardiac FAAH activities increased in both models of hypertension like in our previous study." (PMID 32075117, 2020). "Therefore, the FAAH inhibitor URB597 may be a useful potential therapeutic compound for counteracting the effects of hypertension." (PMID 32664225, 2020). "By contrast, the dual FAAH/MAGL inhibitor JZL195, administered to SHR for 2 weeks revealed a weak hypotensive effect and prevented the progression of hypertension." (PMID 38255931, 2024). "Our study showed that hypertension and chronic administration of URB597 caused local, resistance artery-specific beneficial alterations in the vascular endocannabinoid system, which may bring further advantages for therapeutic application of pharmacological inhibition of FAAH." (PMID 34063297, 2021). "In summary, these studies indicate that chronic administration of FAAH inhibitor, URB597, to hypertensive rats modifies the cardiac redox balance depending on the type of hypertension." (PMID 30223427, 2018). "Dual FAAH/MAGL inhibitors follow the new trend in contemporary pharmacology of multi-target-directed ligands as therapeutic compounds suitable for the treatment of complex diseases, including hypertension." (PMID 37446125, 2023). "In conclusion, chronic dual FAAH/MAGL inhibition prevents the progression of hypertension in SHR without affecting some basal functions of the body." (PMID 37446125, 2023). "Therefore, the purpose of this study was to evaluate the effects of chronic administration of the FAAH inhibitor URB597 on the redox system in the brain, and in subsequent modifications of phospholipid metabolism in rats with spontaneous hypertension." (PMID 32664225, 2020). "In this context, one should keep in mind that the FAAH inhibitor URB597 and hypertension may affect cardiac and plasma oxidative stress, endocannabinoid levels and lipid metabolism in a model-dependent manner." (PMID 32075117, 2020). "Thus, when comparing the outcomes of chronic treatment of SHR with URB597 (FAAH blockade only) and JZL195 (dual FAAH/MAGL blockade), increasing 2-AG levels by the inhibition of MAGL might become a new therapeutic option in hypertension." (PMID 38255931, 2024). "Moreover, dual FAAH and MAGL inhibitors are in line with the novel approach of polypharmacology, which proposes multi-target-directed ligands (MTDLs) as potential therapeutic agents, suitable for the treatment of complex diseases, including hypertension." (PMID 37446125, 2023).
Hypertension (continued). "One might assume that the enhancement of the endocannabinoid tone by simultaneous inhibition of FAAH and MAGL might produce more pronounced positive effects on hypertension in comparison to single FAAH inhibition, namely as a result of synergistic actions of AEA and 2-AG." (PMID 37446125, 2023). "Thus, the decrease in their density in aortas in response to the FAAH inhibitor and lack of changes in the hypertension-induced hypertrophy in this vascular bed may be—at least, to some extent—responsible for the lack of hypotensive influence of URB597." (PMID 34063297, 2021). "Furthermore, the use of other models of experimental hypertension may lead to different results, e.g. chronic administration of the FAAH inhibitor URB597 did not affect BP in SHR, but reduced it in the deoxycorticosterone acetate (DOCA)-salt model of secondary hypertension." (PMID 37446125, 2023).
lung carcinoma (7 papers, 2014 to 2023). "Based on the detected elevation of endocannabinoids and endocannabinoid-like substances in FAAH inhibitor-treated lung cancer cells, a potential anti-invasive and TIMP-1-upregulating effect of exogenously added AEA, 2-AG, OEA and PEA was investigated next." (PMID 26930716, 2016). "Like in A549, incubation of H460 or lung cancer patient's metastatic cells with either FAAH inhibitor resulted in a profound suppression of invasion through Matrigel-coated transwell plates." (PMID 26930716, 2016). "A similar anti-invasive TRPV1-dependent impact on lung cancer cells could be proven for FAAH siRNA and the FAAH inhibitors URB597 and N-arachidonoylserotonin (AA-5HT), as well as for CBD." (PMID 31143113, 2019). "In addition, the effect of FAAH inhibition on tumor metastasis of comparable lung cancer models was even superior to thalidomide." (PMID 26930716, 2016). "For example, CB2- and TRPV1-mediated induction of TIMP-1 was confirmed as the mechanism of anti-invasive action for the FAAH inhibitors AA-5HT and URB597, as well as for FAAH siRNA in human lung cancer cells." (PMID 34830856, 2021). "This study addressed the impact of two FAAH inhibitors (arachidonoyl serotonin [AA-5HT], URB597) on A549 lung cancer cell metastasis and invasion." (PMID 26930716, 2016). "The present study therefore investigated the impact of two FAAH inhibitors (URB597, AA-5HT) and four FAAH substrates (AEA, 2-AG, OEA, PEA) on lung cancer cell metastasis and invasion." (PMID 26930716, 2016). "In our present study, we found that FAAH and cannabinoid receptor CB1 are expressed in lung cancer patient samples as well as in NSCLC cell lines." (PMID 24811863, 2014).
alcohol dependence (6 papers, 2017 to 2024). Physical and psychological dependence on alcohol. "An SNV variant (rs324420/C385A) of the FAAH gene was found to establish important risk factors for alcohol dependence and marijuana use." (PMID 38254998, 2024). "These mutant FAAH (A/A) mice developed a greater alcohol intake and preference in the drinking-in-the-dark paradigm (DID), supporting the idea about the involvement of this SNP in alcohol dependence." (PMID 35327588, 2022).
glioma (6 papers, 2009 to 2024). A benign or malignant brain and spinal cord tumor that arises from glial cells (astrocytes, oligodendrocytes, ependymal cells). "C6 glioma cells have a high expression of FAAH and are thus a useful system to study the hydrolysis of internalised AEA." (PMID 24466356, 2014). "After examining the biosynthesis of NAGly in a FAAH-rich in-vitro cellular model (C6 glioma), we sought to determine whether FAAH-dependent biosynthesis of NAGly occurs also in vivo." (PMID 19460156, 2009). "That the levels of NAGly were dramatically decreased in brain after URB 597 and in the FAAH KO mice suggests that the compensatory NAGly production shown in the C6 glioma cells may be an acute phenomenon specific for these cells." (PMID 19460156, 2009). "Incubation with D8AA in C6 glioma cells likewise produced D8NAGly; however, with significantly less efficacy leading to the hypothesis that FAAH-initiated AEA-released AA conjugation with glycine predominates in these cells." (PMID 19460156, 2009). "Therefore, we hypothesized that FAAH may catalyze the biosynthesis of NAGly in C6 glioma cells, a murine cell line that exhibits robust FAAH activity." (PMID 19460156, 2009). "Specifically, CBD treatment suppressed the expression of 5-LOX and increased the production of fatty acid amide hydrolase (FAAH), which led to a reduction in anandamide (AEA) synthesis, ultimately inhibiting the viability of glioma cells." (PMID 38987805, 2024). "In gliomas, the expression pattern and activities of NAPE-PLD (N-acylphosphatidylethanolamine-specific phospholipase D), FAAH (fatty acid amide hydrolase), and MAGL are decreased." (PMID 33916164, 2021). "The AEA downregulation in glioma tissues was correlated with the decrease of activity and expression of NAPE-PLD, the enzyme responsible for AEA synthesis and with a reduced the activity and expression of FAAH, enzyme responsible of AEA degradation." (PMID 33916164, 2021).
melanoma (6 papers, 2012 to 2024). A malignant, usually aggressive tumor composed of atypical, neoplastic melanocytes. "This study suggested the interest of targeting FAAH in the management of melanoma and underlines the advantage of associating endocannabinoids with enzymatic hydrolysis inhibitors." (PMID 38369184, 2024). "Although the role of AC in melanoma progression is well sustained, more studies are necessary to unveil the putative importance of FAAH and NAAA in this disease." (PMID 38369184, 2024). "Although the cannabinoid system has been reported to play a role in melanoma, only two articles have addressed the importance of FAAH and NAAA in melanoma progression." (PMID 38369184, 2024). "By enhancing PEA levels through the inhibition of its FAAH-mediated hydrolysis and by direct administration, we put into light the possibility of potentiating the increase of B16 melanoma cell death and slowing tumor progression." (PMID 22429826, 2012). "Similarly, palmitoylethanolamide (PEA – an endocannabinoid-like lipid mediator) reduced the viability of B16 mouse melanoma cells, which was enhanced by the inhibition of FAAH and thus, the inhibition of PEA hydrolysis." (PMID 38019413, 2024). "The inhibition of tumour cell growth by FAAH inhibition was later also shown in melanoma cells." (PMID 34830856, 2021). "Additionally, it has been reported that N-arachidonoyl-ethanolamine, also known as anandamide (AEA – an endogenous cannabinoid) produced cytotoxicity in A375 melanoma cells, which was enhanced by the inhibition of fatty acid amide hydrolase (FAAH), an enzyme degrading AEA." (PMID 38019413, 2024). "Therefore, we assayed five inhibitors of either FAAH or NAAA, the two main enzymes known to hydrolyze PEA and that we found to be expressed in B16 melanoma cells." (PMID 22429826, 2012). "Thus, a study demonstrated concentration-dependent apoptosis of melanoma cells after incubation with AEA, which was enhanced by inhibition of FAAH and attenuated by blockade of COX-2 or lipoxygenase (LOX), suggesting involvement of eicosanoid metabolism in this endocannabinoid effect." (PMID 34830856, 2021).
brain injury (5 papers, 2021 to 2025). Acute and chronic (see also brain INJURIES, CHRONIC) injuries to the brain, including the cerebral hemispheres, CEREBELLUM, and brain STEM. "It has been reported that the FAAH inhibitor, URB597, has anti-inflammatory and antioxidant effects during ischemic stroke and traumatic brain injury." (PMID 38214766, 2024). "In addition, the use of PF-3845 as an irreversible FAAH inhibitor downregulated the expression of iNOS and COX-2 after traumatic brain injury." (PMID 34299330, 2021).
cannabis dependence (5 papers, 2021 to 2025). Physical and psychological dependence on the drug cannabis. "The most consistent genetically mediated effects appear to be illuminated in a small body of literature implicating a functional polymorphism within FAAH to cannabis dependence as well as withdrawal symptoms and responses to acute THC administration." (PMID 38541766, 2024). "The FAAH rs324420 variant has also been linked to substance use disorders, specifically cannabis dependence, and that altered FAAH activity has been shown to influence alcohol use, although findings are still complex and controversial." (PMID 37895295, 2023). "Current evidence shows promising therapeutic effects of FAAH inhibitors in nicotine and cannabis dependence." (PMID 41282260, 2025).
epilepsy (5 papers, 2017 to 2025). A brain disorder characterized by episodes of abnormally increased neuronal discharge resulting in transient episodes of sensory or motor neurological dysfunction, or psychic dysfunction. "In all patients with epilepsy, 81 cases of FAAH rs324420 were wild type (CC), and 24 cases had gene mutations, including 20 cases of heterozygous mutations (CA) and 4 cases of homozygous mutations (AA)." (PMID 39920787, 2025). "NR3C1 rs41423247 and FAAH rs324420 polymorphisms were detected by the polymerase chain reaction in 105 pediatric epilepsy patients." (PMID 39920787, 2025). "The FAAH rs324420 polymorphism has also been related to other neural dysfunctions, such as epilepsy and attention deficit hyperactivity disorder (ADHD)." (PMID 37895295, 2023). "Thus, future studies should take into account external factors and observe the relationship between NR3C1 and FAAH genetic polymorphisms and epilepsy drug response after controlling for these factors." (PMID 39920787, 2025). "This study investigated the relationship between drug response to epilepsy treatment and the rs41423247 polymorphism on the NR3C1 gene or the SNP rs324420 on the FAAH gene." (PMID 39920787, 2025). "Although relatively few direct studies have been conducted on the role of FAAH in patients with different types of epilepsy, its role in epilepsy warrants further investigation because it is a key enzyme in the endocannabinoid system." (PMID 39920787, 2025). "Therefore, in the future, large-scale clinical studies can be conducted to collect NR3C1 and FAAH gene information and epilepsy drug treatment response data, and analyze the relationship between NR3C1 and FAAH gene polymorphisms and epilepsy drug response." (PMID 39920787, 2025). "In our study, the FAAH rs324420 polymorphism did not correlate with drug response after ASM treatment in patients with epilepsy These results suggest that polymorphisms in FAAH do not correlate with drug response to ASM therapy for epilepsy." (PMID 39920787, 2025). "Nowadays, the SNPs in NR3C1 and FAAH on the drug response of epilepsy remain unclear." (PMID 39920787, 2025). "Then explore the personalized epilepsy treatment strategy based on NR3C1 and FAAH." (PMID 39920787, 2025). "The novel fatty acid amide hydrolase inhibitor, URB-597, has been demonstrated to produce anticonvulsant effect on seizures induced by pentylenetetrazole in rats, and to block neuronal hyperactivity in neurons, which can be considered a similar mechanism to that seen in epilepsy." (PMID 29209207, 2017).
Headache (5 papers, 2022 to 2026). Cephalgia, or pain sensed in various parts of the head, not confined to the area of distribution of any nerve. "Targeting fatty acid amide hydrolase (FAAH) is a promising therapeutic strategy to combat certain forms of pain, including migraine headache." (PMID 35799128, 2022). "Preclinical evidence suggests fatty acid amide hydrolase (FAAH) enzyme as a potential therapeutic target for migraine headache." (PMID 35799128, 2022). "Pharmacological strategies targeting endocannabinoid degradation, such as inhibition of FAAH, MAGL, and COX-2, enhance endogenous cannabinoid tone and consistently reduce headache-like behaviors across diverse models." (PMID 41744774, 2026). "Previous studies have shown that FAAH inhibitors that act by increasing endocannabinoid levels and extending their duration of action without eliciting the psychoactive effects related to direct CB1 receptor activation may offer a promising treatment option for headaches." (PMID 35563056, 2022).
Huntington disease (5 papers, 2014 to 2021). Huntington disease (HD) is a rare neurodegenerative disorder of the central nervous system characterized by unwanted choreatic movements, behavioral and psychiatric disturbances and dementia. "We detected an increase in FAAH mRNA expression in the whole striatum at 32 and 56 weeks, a change also seen in patients and animal models of Huntington’s disease." (PMID 28448548, 2017).
ischemia (5 papers, 2016 to 2022). A hypoperfusion of the BLOOD through an organ or tissue caused by a PATHOLOGIC CONSTRICTION or obstruction of its BLOOD VESSELS, or an absence of BLOOD CIRCULATION. "This latter strategy was effective in reducing RGC damage as a result of transient high IOP-induced ischemia whereby RGC loss was attenuated by administration of the FAAH inhibitor URB597." (PMID 26881140, 2016). "Moreover, FAAH inhibition was found to have neuroprotective effects in rat models of high intraocular pressure (IOP)-induced ischemia and optic nerve axotomy by enhancing eCB levels that acted on both CB1Rs and TRPV1 channels." (PMID 36231760, 2022). "Recently, the FAAH inhibitor URB597 and AG have important regulatory effects on neuronal and vascular cells in ischemia." (PMID 35602108, 2022).
metabolic syndrome (5 papers, 2010 to 2025). A cluster of metabolic risk factors for CARDIOVASCULAR DISEASES and TYPE 2 DIABETES MELLITUS. "FAAH and MGL activity were not different between ‘healthy’ patients and those with metabolic syndrome or diagnosed T2M." (PMID 24593280, 2014). "By contrast, in severely obese humans, FAAH and MGL activity in adipose tissue was not correlated with adiposity and were not different between ‘healthy’, type 2 diabetic, metabolic syndrome patients, or in patients with clinical elevated blood glucose, poor glycaemic control or hyperlipidaemia." (PMID 24593280, 2014).
multiple sclerosis (5 papers, 2014 to 2025). A progressive autoimmune disorder affecting the central nervous system resulting in demyelination. "Investigation of CBR in brain tissue samples from multiple sclerosis patients showed that CB1R- and CB2R-expressing cells are collected in active multiple sclerosis plaques and FAAH enzyme activity is induced." (PMID 32508955, 2020).